RXRA (retinoid X receptor alpha)
Diseases named in the same sentence as RXRA in open-access papers (continued):
Sharing a sentence is not in itself a finding about the gene and the disease.
cancer (continued). "The findings indicated that these furocoumarin skeleton derivatives might hold beneficial effects on many intractable diseases, such as cancer and metabolic diseases, due to their potential activities on regulating the transcriptional activation function of RXRα." (PMID 21792151, 2011). "Therefore, phosphorylation of RXRα was only specific in cancer cells, which could be a reason for the selective apoptosis of cancer cells by ACR treatment." (PMID 21214951, 2011). "For instance, BPA-B9 has been identified as a potent and selective RXRα antagonist (KD~39 nM), disrupting the RXRα/PLK1 interaction critical for mitotic progression and inducing mitotic arrest in cancer cells." (PMID 41227299, 2025). "On the contrary, some core kinases and transcription factors involved in cancer such as CDK6, ERBB2, JAK1, DAPK1, FOXO1, and RXRA were highly expressed in S-III." (PMID 38143770, 2023). "We also found that KRT7-AS gene transcription was driven by the transcription factor RXRα; intriguingly, the small molecule berberine enhanced KRT7-AS expression, reduced tumorigenesis, and promoted apoptosis of cancer cells." (PMID 37185462, 2023). "Our own findings on RXRα/PPARγ cytoplasmic coexpression showed that it was significantly correlated with CD133, a widely used marker for cancer stem cell (CSC)." (PMID 35406808, 2022). "RXRα expression was examined using immunohistochemistry staining on the biopsied sections of AKI patients; para-carcinoma kidney tissues were used as controls." (PMID 36443310, 2022). "Subsequently, the bioinformatics analysis based on the IPA database revealed that the most enriched canonical signaling pathway is “PPARα/RXRα activation” and “AMPK signaling”, while the most enriched IPA disease and function is “cancer”." (PMID 33414423, 2021). "The top 5 important TFs observed in more than 10% of all cancer genomes include SP1, RXRA, NR2F2, GABPA, and CTCF." (PMID 33647036, 2021). "Further insight into the cancer-related gene expression unraveled that 22 of DEGs were upregulated by shNrf1, of which 4 genes (i.e., RAC3, PDGFA, GSTA4, and RXRA) were downregulated by Nrf1α−/− (, and )." (PMID 32273945, 2020). "Cancer tissues had lower E‐cadherin and higher vimentin, Snail and ZEB‐1 expression than para‐carcinoma tissues suggesting that EMT, along with a down‐regulation of RXRα expression, was promoted in cancer tissues." (PMID 33128348, 2020). "Unexpectedly, three cancer related-pathways genes (Tal1, PPAR-γ, and RXRA) were identified as hub genes in neonates." (PMID 31456798, 2019). "This tRXRα (RXRα-Δ80) can interact with the p85α subunit of the PI3K/AKT survival pathway and promote cancer cell proliferation in the majority of cancer cells." (PMID 30093910, 2018). "To find a possible link between these three cancers subjected to arsenicals exposure, we merged the three networks and identified seven HUB nodes (RXRA, MAP3K7, NR3C1, PABPC1, NDRG1, RELA and CTNNB1) of the linking region between three cancer networks." (PMID 29991691, 2018). "Taken together, our results identify a new RXRα antagonist with abilities to modulate TR3 functions indirectly by binding to RXRα and to convert TNFα signal to induce cancer cell apoptosis by targeting tRXRα." (PMID 26156677, 2015). "Whether RXRA upregulation by TTC7B might enhance the therapeutic efficacy of ATRA- and RXRA agonist-mediated treatments for cancers is worthy of study." (PMID 39897037, 2025).
cancer (continued). "This study reveals a novel RXRα antagonist, 7i, which targets RXRα and induces G2/M phase cell cycle arrest in MDA-MB-231 cells, showing potential as a lead candidate for the development of anti-cancer agents." (PMID 41003337, 2025). "Retinoic acid receptor alpha (RARA) and retinoid X receptor alpha (RXRA), which negatively correlate with POLR3G expression across cancers, are retinoid-activated nuclear receptors that mediate transcriptional programs by forming homo- and heterodimers in the presence or absence of specific ligands." (PMID 37894362, 2023). "In conclusion, PCBs can interfere with thyroid hormone dysfunction by regulating MAPK3, MAPK1, RXRA, PIK3R1, and other potential targets, as well as the cancer pathway, PI3K-Akt signaling pathway, thyroid hormone signaling pathway, prolactin signaling pathway, and FoxO signaling pathway." (PMID 36203481, 2022). "In addition to the well-established ER and PR, other NRs, including retinoid X receptor (RXRα), peroxisome proliferator-activated receptor (PPAR), vitamin D receptor (VDR), and others, play notable roles in the pathophysiology of BC and other cancer entities." (PMID 35406808, 2022). "Concerning transcription factors, sets of the most important features are less similar to each other for different cancer types but nevertheless CTCF, GABPA, RXRA, SP1, MAX and NR2F2 are more frequently included in top features than other transcription factors." (PMID 33647036, 2021). "The results showed that a lower RXRα expression in cancer tissues, and a moderate negative correlation between RXRα and N stage, and tended to higher level of EMT." (PMID 33128348, 2020). "We assumed that RXRα may be targeted by 20(S)‐PPD, as RXRα can be inhibited by modulating the PI3K/Akt signalling pathway through Akt and FAK phosphorylation in cancer cells." (PMID 33128348, 2020). "RXRα is a nuclear transcription factor that is normally downregulated in several tumors, including colon carcinoma, therefore, EGCG therapy can be seen as a chemoprevention strategy in cancer." (PMID 30627525, 2018). "Notably, the RXRA protein was in protein complexes with RARA, PPARG, NCOA1, NCOA2, and NCOR2 cancer drivers." (PMID 29572294, 2018). "RXRA, CDKN1A, and RHOA are the members of pathways in cancer." (PMID 29738475, 2018). "Here the authors show that the anti-cancer agent K-80003 selectively inhibits the nongenomic action of N-terminally-cleaved RXRα in tumour cells by stabilizing its tetramerization but not that of full-length RXRα." (PMID 28714476, 2017). "Surprisingly, unlike classic oncogenic pathways that promote cancer cell proliferation, PPARγ/RXRα alterations slightly reduced cell growth in vitro." (PMID 28740126, 2017). "Interestingly, cancer immunity-related cytokine and antigen processing/presentation pathways were commonly downregulated in MIBC bearing RXRA or PPARG alterations." (PMID 28740126, 2017). "We previously discovered that an N-terminally-cleaved form of RXRα (tRXRα), produced in tumour cells, activates phosphoinositide 3-kinase (PI3K) signalling by binding to the p85α subunit of PI3K and that K-80003, an anti-cancer agent, inhibits this process." (PMID 28714476, 2017). "One candidate is the truncated form of RXRα, t-RXRα which has been described as being located in the cytoplasm and as acting non-genomically on cancer cell growth and resistance." (PMID 26450852, 2015). "In cancer cells, a truncated RXRα (tRXRα) that results from incomplete proteolytic processing of RXRα also exists, and can act non-genomically through interaction with other proteins to drive tumor cell survival and proliferation." (PMID 23875171, 2013).
cancer (continued). "Transcriptomics and proteomics as a whole identified key DEPs of the THRB(−/−)/RL95-2 cells, including cellular junctions, metabolism, and cancer-related pathways, suggesting RARβ, CRABP2, and RXRA could be potential targets for MPA resistance and targeted by CANA." (PMID 40371351, 2025). "Binding motifs for many essential TFs, such as RXRA, NFE2L2, ESRRA, IRF2, RELA, ESRRA, SOX2, and SMAD2/3, key TFs that mediate TGFβ signaling in epithelial-mesenchymal transition (EMT) and cancer metastasis, were enriched in common gained or LNC-specific gained enhancers, with some overlapping TFs." (PMID 34294701, 2021). "Previous studies reported that there was a lack of RXRα expression in cancer tissues." (PMID 33128348, 2020). "MRx 102, a triptolide derivative with C-14-hydroxyl modification of amine ester group, differentially regulates the expression of retinoid X receptor-α (RXRα) but not the level of full length of RXRα, and inhibits cancer cell growth through the inhibition of AKT signaling pathway." (PMID 29491837, 2018). "They suggested that nongenomic action of an N-terminally truncated RXRα (tRXRα) could play a role in the crosstalk with TNFα signaling in cancer cells." (PMID 30103423, 2018). "Importantly, this analysis additionally identified a number of instances that are not in the Cancer Gene Census yet, including RXRA and CARM1." (PMID 29572294, 2018). "Interestingly, the three other proteins RXRA, BCL11A and ELK1 are also related to cancer." (PMID 27203237, 2016). "The selective induction by K-80003 of the tetramerization of tRXRα but not RXRα suggests that this class of compounds may preferentially affect tRXRα activity, which is therapeutically desirable since tRXRα is often overproduced in cancer cells." (PMID 28714476, 2017). "We also focus on the phosphorylation of RXRα because the inhibition of RXRα phosphorylation and the restoration of its physiological function may activate PPAR/RXR heterodimer and, therefore, be a potentially effective and critical strategy for the inhibition of cancer cell growth." (PMID 18528526, 2008).
tumor (103 papers, 2007 to 2025). "PFOS increased carcinogenic risk, tumor progression and spheroid formations in the prostate gland as well as increased the expression of PPARα and RXRα." (PMID 41228300, 2025). "Co-expression of nuclear RXRα and cytoplasmic (p = 0.026) or nuclear (p = 0.041) Sirt1 was associated with significantly increased overall survival in advanced tumour stages." (PMID 34870752, 2022). "As shown in the Kaplan–Meier curve, co-expression of Sirt1 and nuclear RXRα was associated with significant longer survival time after diagnosis in advanced tumour stages (FIGO III/IV)." (PMID 34870752, 2022). "In the nucleus, RXRα was significantly and negatively associated with tumor size (pT) (p = 0.012; Cc = −0.143)." (PMID 34359656, 2021). "Nuclear RXRα expression, on the other hand, was significantly positively associated with a decreased tumor size, as well as lower pathological staging for distant metastases and regional lymph node involvement." (PMID 34359656, 2021). "Amplified / overexpressed mutated RXRA-PPARG would modulate the tumor microenvironment and lead to resistance to immunotherapy." (PMID 33024200, 2020). "Third, LINC00511 can accelerate tumor progression through regulating several tumor-associated signaling pathways such as RXRA/PLD1, PTEN/AKT/FOXO1, p38, ERK1/2 and JNK pathways." (PMID 32713253, 2020). "We detected a comparable PPARG mutation rate, 3.1% of the tumors (14/455), but a higher RXRA mutation rate, 6.1% of the tumors (28/455) in these tumor series compared to the previous tumor series analyzed." (PMID 30651555, 2019). "Here, we report that the PPARγ/RXRα pathway constitutes a tumor-intrinsic mechanism underlying immune evasion in MIBC." (PMID 28740126, 2017). "PPARD agonist and mutant RXRA confer growth-factor-independent growth to urothelium in the context of tumor suppressor loss." (PMID 29143738, 2017). "More intriguingly, the level of GRP75/RARα/RXRα tripartite complexes was tightly associated with the RA-induced suppression of tumor growth in animals and the histological grade of differentiation in human NB tumors." (PMID 22022577, 2011). "Additionally, cytoplasmic RXRα expression was positively associated with a higher histopathological tumor grading (p = 0.02)." (PMID 34359656, 2021). "In addition, the RXRα hotspot mutations stimulate the proliferation of urothelial organoids, render bladder tumor cell growth PPARγ-dependent, and favor tumor evasion by the immune system." (PMID 33716977, 2021). "We believe that RXRA S427F mutation may play an important role in tumor initiation and progression." (PMID 30176882, 2018). "In addition, dysfunctions or abnormal expressions of RXRα are implicated in tumor development." (PMID 26156677, 2015). "Significant loss of RXRα was evident in tumors as well as in tumor-free areas of intestine after 56Fe radiation and this could contribute to decreased proteasomal targeting of β-catenin, therefore enhancing cell survival and proliferation through β-catenin/TCF4 signaling." (PMID 26500891, 2015). "Retinoid X receptor α (RXRα) plays a vital role in multiple biological and pathological processes and represents a promising therapeutic target for anti-tumor drug design." (PMID 41003337, 2025). "Variations in the dynamics of VDR nuclear translocation and its colocalization with RXRA, observed between tumor cells and healthy keratinocytes, guided the selection of optimal time points for transcriptomic investigations." (PMID 40724881, 2025). "The inhibitory effects of 21 derivatives on RXRα transactivation and their anti-tumor activities against MDA-MB-231 cells were evaluated." (PMID 41003337, 2025). "In line with the in vitro results, ZBTB16 and PPARγ, RXRα protein levels were both increased, which confirmed that PPI effectively inhibits tumor growth by targeting ZBTB16 to activate the PPARγ/RXRα signaling pathway." (PMID 39182119, 2024).
tumor (continued). "The “PPARα/RXRα activation” and “LXR/RXRα activation” canonical pathways were also predicted to be inhibited in Pparg-/-epi mouse skin and the tumor datasets." (PMID 39195246, 2024). "Reduced PPAR activity was also associated with reduced PPARα/RXRα activity, while LPS/IL1-mediated inhibition of RXR activity was significantly activated in the tumor datasets." (PMID 39195246, 2024). "Numerous studies have confirmed that several antitumor agents can target RXRα to regulate cell cycle distribution and inhibit the proliferation of tumor cells." (PMID 36874033, 2023). "VDR expression highly correlated with the histological differentiation of the tumor, in contrast to the RXRα levels (n = 540, p = 0.0002 ***/p = 0.0056 **)." (PMID 36902107, 2023). "PPARγ functions as a tumor-suppressive factor via PPARγ/RXRα signaling pathway in several tumor types." (PMID 37976136, 2023). "Studies have suggested that regulation of subcellular localization of retinoid X receptor-alpha (RXR-α) is a potential method to induce tumor cell apoptosis." (PMID 37795026, 2023). "But it is well known, that its stimulation with retinoids and a high amount of RXRα lead to an inhibition of tumour growth." (PMID 34870752, 2022). "Another study reported the overexpression of RXRα in cancer cells, and RXRβ expression, on the other hand, reduced in 18% of tumor samples." (PMID 35631448, 2022). "The mRNA expression of genes of RXRγ, RARα, and RXRα was shown to be considerably lower in tumor specimens, revealing that deregulation of these genes follows the aberrant transformation of lung tissue cells." (PMID 35631448, 2022). "One such study determined the expression of RARs in normal and malignant tissues from 76 patients with NSCLC and showed that tumor cells have overexpressed RXRα and RARα and reduced RXRβ, RARβ, and RARγ." (PMID 35631448, 2022). "Cox univariate analysis indicated that patients with tumors coexpressing RXRα and PPARγ in the cytoplasm of tumor cells have a decreased 5 y OS rate." (PMID 35406808, 2022). "A positive correlation was observed between high cytoplasmic RXRα expression and higher histopathological tumor grading (p = 0.029; Cc = 0.125)." (PMID 34359656, 2021). "Recent studies have shown that RXRα can be truncated by restrictive hydrolysis in many tumor cells, to produce RXRα with missing N-terminus, called tRXRα (truncated RXRα)." (PMID 34539418, 2021). "A previous study has shown that the hub gene RXRA can influence cell differentiation, cell migration, and provoke tumor suppression via the PI3K-Akt signaling pathway." (PMID 33506873, 2021). "In our study, cytoplasmic RXRα expression was strongly positively correlated with higher histopathological tumor grading." (PMID 34359656, 2021). "On the tissue level, an increased expression of this MiR was demonstrated, correlating negatively with RXRα, and positively with various clinical (clinical-stage, distant metastasis, patients’ survival) and histological data (tumor differentiation)." (PMID 33276489, 2020). "The authors found that the mRNA levels of the nuclear receptor genes RXRγ, RARα, RXRα were significantly decreased in 80%, 65%, and 57% of tumor specimens, respectively, even at early stages." (PMID 32012980, 2020). "The abnormal cleavage of retinoic acid X receptor-alpha (RXRα) in tumor cells and tissues produces a truncated RXRα (tRXRα) with a tumorigenic effect, mainly due to its expression in bone marrow cells leading to IL-6 induction and STAT3 activation." (PMID 33294443, 2020). "Andrastone A showed significant inhibitory effect selectively against HepG2 tumor cells by activating caspase-3 and regulating the transcriptional activation function of RXRα." (PMID 31737594, 2019). "We previously discovered that RXRα is abnormally cleaved in tumor cells and tissues, producing a truncated RXRα (tRXRα)." (PMID 30931933, 2019).